HDAC3 (histone deacetylase 3)
Diseases named in the same sentence as HDAC3 in open-access papers (continued):
Sharing a sentence is not in itself a finding about the gene and the disease.
multiple myeloma (18 papers, 2014 to 2025). "For example, in multiple myeloma, bortezomib enhances apoptosis through targeting HDACs, predominantly through the downregulation of HDAC3." (PMID 38672531, 2024). "The results indicate that the spatially restricted turnover of HDAC3 at defined chromatin sites dictates activity of genes important for multiple myeloma growth." (PMID 36846090, 2022). "Our observations imply that HDAC3 can slow multiple myeloma growth and energy metabolism by repressing cell-cycle and mitochondrial genes following proteasome inhibition." (PMID 36846090, 2022). "Our studies indicate a novel therapeutic function of proteasome inhibitors in multiple myeloma by reshaping the epigenetic landscape in an HDAC3-dependent manner." (PMID 36846090, 2022). "When analyzing HDAC3 and SIAH2 transcript expression profiles in 1,457 cancer cell lines, including 27 multiple myeloma cell lines, in the Cancer Cell Line Encyclopedia, we found that high levels of SIAH2 were associated with low HDAC3 expression." (PMID 36846090, 2022). "It is reported that the knockdown of HDAC3 in BMSC-derived exosomes results in the decreased multiple myeloma cell proliferation, and the delivery of miR-143 by BMSC-derived exosomes suppresses osteosarcoma cell (143B cell line) migration." (PMID 31699956, 2019). "The genetic silencing or pharmacological inhibition of HDAC3 leads to the suppression of myeloma cell proliferation." (PMID 30987296, 2019). "Because SIAH2 directly interacts with HDAC3, it may derepress proliferative and metabolic genes and represent a target of clinical interest in multiple myeloma." (PMID 36846090, 2022). "Interestingly, we found that alteration of HDAC expression in bortezomib-resistant myeloma cells is heterogeneous, such that HDAC3, 4, 5, 7, 9, 10, and 11 are downregulated while HDAC2 and 6 are upregulated." (PMID 34888496, 2021). "Moreover, depletion or pharmacological inhibition of HDAC3 triggered apoptosis in cutaneous T-cell lymphoma and multiple myeloma." (PMID 33298132, 2020). "Therefore, combination with HDAC3-selective inhibitor plus CD26mAb may be a promising therapeutic option to induce enhanced myeloma cell growth by CD26mAb." (PMID 38284882, 2024). "Besides, inhibition of HDAC3 expression can decrease the proliferation of myeloma and CCA cells." (PMID 35126526, 2022). "Moreover, when treated with proteasome inhibitors, the loss of H3K27 acetylation was significantly attenuated when HDAC3 was knocked down compared with nonsilencing multiple myeloma cells." (PMID 36846090, 2022). "In multiple myeloma and HCC, the ubiquitin ligases SIAH2 and TRAF6 can degrade HDAC3 through ubiquitination, enhancing H3K27 and H3K9 acetylation levels in the c‐myc promoter region and thereby promoting c‐myc transcription." (PMID 39778006, 2025). "The efficacy of this combination treatment was confirmed in vivo using a murine xenograft MM model and the rationale for combined treatment using HDAC3 and DNMT1 inhibitors, as a novel strategy for myeloma therapy, was suggested." (PMID 30987296, 2019). "In particular, HDAC3 has been reported to regulate c-Myc protein levels, thereby HDAC3 inhibition increased acetylation of c-Myc as well as DNMT1 in myeloma cells, leading to degradation of DNMT1 and inhibition of myeloma cell growth." (PMID 38284882, 2024). "Histone modification is considered an important transcriptional regulatory mechanism and is involved in the progression of multiple tumors, for example, HDAC3-mediated deacetylation leads to ENO2 activation in pancreatic cancer, and the HDAC4-RelB-p52 complex regulates multiple myeloma growth." (PMID 35892859, 2022). "Combined HDAC3 inhibitor and AZA, a DNMT1 inhibitor, was found to synergistically downregulate DNMT1, resulting in the growth inhibition and apoptosis of MM cell lines and myeloma patient-derived cells." (PMID 30987296, 2019).
multiple myeloma (continued). "Further research by Matthew Ho and his team demonstrated that disabling Histone deacetylase 3 (HDAC3) via knock-out (KO), knock-down (KD), or pharmacological methods in BMSCs reduces myeloma cell proliferation, effectiveness confirmed in patient-derived myeloma cell cultures with BMSCs." (PMID 38900304, 2024). "ChIP-seq assays showed that acetylation of H3K27 at cell cycle/mitochondrial gene promoters and super-enhancers of genes relevant for multiple myeloma biology (c-MYC, BCL-XL, CCND2, IRF4, MCL1, PIM1, PRDM1, and XBP1) was mildly increased in HDAC3 knockdown cells compared with nonsilencing cells." (PMID 36846090, 2022).
pancreatic cancer (17 papers, 2009 to 2024). "Previously, we found that the RB–p65 axis 10, FUBP1–Myc axis 20, HAT1–BRD4 axis 21 or HDAC3 22 regulated PD‐L1 expression in pancreatic cancer." (PMID 31898405, 2020). "Our previous study found that EZH2 and HDAC3 were negatively correlated with the prognoses of pancreatic cancer patients." (PMID 33299646, 2020). "Here, we investigate the prognostic significance of aberrant CDH1 and HDAC3 localization in 84 pancreatic cancer patients." (PMID 26918727, 2016). "Similarly, overexpression of HDAC2 has been shown to promote the migration and invasion of non-small cell lung cancer cell lines, and overexpression of HDAC3 has been reported to promote the proliferation of cholangiocarcinoma and pancreatic cancer cell lines." (PMID 35646715, 2022). "Notably, HDAC3 inhibitors are considered as a promising candidate for immunity-based therapy in pancreatic cancer." (PMID 36266728, 2022). "Furthermore, the expression of HDAC1 has been reported to correlate with the progression and prognosis of gastrointestinal malignancies; and HDAC3 also has been suggested as a prognostic marker in gastric, colorectal, and pancreatic cancer." (PMID 35646715, 2022). "However, one study showed that the HDAC3/STAT3 pathway transcriptionally regulates PD-L1 expression in pancreatic ductal adenocarcinoma, and HDAC3 inhibitors reduce the protein and mRNA levels of PD-L1 in pancreatic cancer cells." (PMID 34880761, 2021). "We speculate that first, pancreatic tumor cells may have escaped apoptosis, at least in part, through HDAC3 overexpression in cell nucleus." (PMID 26918727, 2016). "In line with previous studies of our group, which focussed on HDAC expression in malignancies of other organs like prostate and colon, pancreatic tumor tissue displayed a high degree of class I HDAC expression with HDAC3 being the most abundantly expressed isoform." (PMID 19912635, 2009). "Additionally, HDAC3 upregulates PD-L1 expression through the STAT3 pathway in pancreatic cancer." (PMID 38762484, 2024). "Our studies provide convincing evidence that nuclear HDAC3 and cytoplasmic CDH1 have independent prognostic value in pancreatic cancer and provide novel targets for prognostic therapeutics." (PMID 26918727, 2016). "Using an HDAC3 inhibitor or knocking down HDAC3 weakens the binding of STAT3 to the PD-L1 promoter, thereby destroying the HDAC3/STAT3/PD-L1 signal transduction and improving the immunotherapy efficacy in pancreatic cancer." (PMID 38762484, 2024). "In addition to the HDAC1/HDAC2-dependent transcriptional regulation of MYC in pancreatic carcinoma cells, our data collected with RGFP966 suggest that HDAC3 supports the expression of MYC in leukemic cells." (PMID 31561534, 2019). "Increased nuclear, not cytoplasmic HDAC3 has been found in pancreatic cancer tissues and correlated with an advanced clinical stage and worse prognoses." (PMID 28771976, 2017).
ovarian carcinoma (16 papers, 2012 to 2025). A malignant neoplasm originating from the surface ovarian epithelium. "In a chemotherapy-resistant ovarian cancer A2780-AD cell model, the use of HDAC3 inhibitors significantly increased the expression of OX-40L and 4-1BBL in the cells." (PMID 40006729, 2025). "The expression of HDAC3 was negatively correlated with the expression of E-cadherin, which can affect the invasion and migration of ovarian cancer cells." (PMID 37894746, 2023). "In ovarian cancer, the expression level of HDAC3 was significantly correlated with the expression level of FOXA1." (PMID 37894746, 2023). "In a previous study, HDAC1 and HDAC3 were found to bind at the 4-1BBL promoter to downregulate 4-1BBL expression in chemoresistant ovarian cancer cells, resulting in immune escape and suppression." (PMID 35585975, 2022). "HDAC3 inversely correlates with CDH1 expression in ovarian carcinoma, and HDAC3 siRNA knock down in ovarian carcinoma cells reduced cell migration and increased CDH1 expression." (PMID 26918727, 2016). "This review summarizes the role of HDACs in ovarian cancer and the potential niche for selective class I HDACi, particularly HDAC3 in ovarian cancer therapy." (PMID 24904826, 2014). "We have shown previously that siRNA knockdown of HDAC3 in ovarian cancer cells contributes to suppression of cell proliferation." (PMID 22531354, 2012). "Besides, histone deacetylase 3 (HDAC3) is overexpressed in ovarian cancer, inducing the WFDC2 expression and binding to it." (PMID 39296934, 2024). "It was reported that FOXA1 could be modulated by HDAC3 through the Wnt/β-catenin signaling in ovarian carcinoma." (PMID 37876590, 2023). "In this study, we wanted to explore the function of FOXA1 in ovarian cancer and the relationship between HDAC3 and FOXA1.The expression of HDAC3 and FOXA1 was detected by immunohistochemical staining of primary lesions from 127 epithelial ovarian carcinoma patients." (PMID 34991620, 2022). "Another study demonstrated that HDAC1 and HDAC3 can bind at the OX40L promoter to downregulate OX40L expression in chemoresistant ovarian cancer cells, which could potentially induce the immunosuppression of cancer cells to escape from immune responses." (PMID 35585975, 2022). "This review summarizes the role of histone deacetylase inhibitors (HDACi) as epigenetic anti-cancer therapy and evidence that class I selective HDACi, particularly those biased to HDAC3 may be a promising therapeutic strategy for ovarian cancer." (PMID 24904826, 2014). "Observations in ovarian cancer cells and other cancer cell types indicate that selective targeting of HDAC3 may be an attractive therapeutic strategy." (PMID 24904826, 2014). "If class I selective HDACi biased to HDAC3 can be designed to improve efficacy in subtypes of ovarian cancer such as in HR deficient ovarian tumors without significantly increasing toxicity, the therapeutic impact could be high." (PMID 24904826, 2014). "Studies have demonstrated that HDAC3 inhibition can enhance the efficacy of PARP inhibitors in breast and ovarian cancers by disrupting DNA repair mechanisms, rendering cancer cells more vulnerable to DNA damage." (PMID 40006729, 2025). "The histone deacetylase 3 (HDAC3) and HE4 are both present in the nucleus and cytosol of cellular fraction and is known that HDAC3 promotes proliferation, invasion and migration in ovarian cancer cells." (PMID 37445657, 2023). "The H-scores for FOXA1 and HDAC3 staining in FIGO stage III-IV were noticeably higher and predicted adverse clinical outcomes in patients with ovarian cancer." (PMID 34991620, 2022). "It has been reported that the combination of HDAC3 and HE4 activated the PI3K/AKT pathway in ovarian cancer." (PMID 35136419, 2022). "It has been reported that the combination of HDAC3 and HE4 activates the PI3K/AKT pathway in ovarian cancer." (PMID 35136419, 2022).
ovarian carcinoma (continued). "HDAC3 activates the PI3K/AKT signaling pathway by combining with human epididymis protein 4 (HE4) to promote the proliferation, invasion and migration of ovarian cancer cells." (PMID 36505774, 2022). "The expression levels of HDAC3 and FOXA1 were significantly increased in ovarian cancer recurrence (HDAC3: p < 0.001, FOXA1: p = 0.002) and predicted adverse clinical outcomes in patients with ovarian cancer (HDAC3: p < 0.001, FOXA1: p < 0.001)." (PMID 34991620, 2022).
renal fibrosis (16 papers, 2021 to 2026). A final common manifestation of a wide variety of chronic kidney diseases characterized by glomerulosclerosis and tubulointerstitial fibrosis. "Altogether, the data implicate a key role of HDAC3 in renal fibrosis and associated inflammation." (PMID 39050859, 2024). "Here, we identify histone deacetylase 3 (HDAC3) as a critical epigenetic suppressor of RASAL1 expression in FMT of renal fibrosis." (PMID 41624795, 2026). "Certain HDAC isoforms, such as HDAC3, 4, 6, 8 and 9, are upregulated in injured kidneys and contribute to renal fibrosis." (PMID 41275091, 2025). "Although the role of HDAC3 selective inhibitors in treating renal fibrosis has been explored and appears to be a viable option, their potential role in AKI and the underlying mechanism are yet to be determined." (PMID 40351427, 2025). "A role of the complex formed by HDAC3 and Smad2/3 and NcoR in renal fibrosis has also been demonstrated in patients with focal segmental glomerulosclerosis who show high levels of elevated HDAC3." (PMID 38474021, 2024). "In the UUO model, the HDAC3 inhibitor RGFP966 inhibits renal fibrosis by restoring KLOTHO expression through the inhibition of KLOTHO transcriptional regulators (Ncor and NF-κb)." (PMID 38929505, 2024). "Decreasing miR-19b expression has been shown to facilitate the transdifferentiation of HSCs into myofibroblasts, while the removal of HDAC3 has been found to alleviate fibrosis through the interaction of miR-19b-3p with the 3′-UTR of HDAC3 in renal fibrosis." (PMID 39195573, 2024). "HDAC3 inhibitors can reverse M2 polarization and the phagocytic activity of macrophages and alleviate renal fibrosis." (PMID 37455912, 2023). "To investigate the possible cause of HDAC3 upregulation, we focused on the TGF-β1 signaling pathway since TGF-β1/SMAD3 signaling has previously been reported to directly promote HDAC3 transcription in renal fibrosis." (PMID 37951958, 2023). "Upregulation of HDAC3 is found in injured podocytes, renal fibrosis, chronic kidney diseases (CKDs), and various cancers, indicating that HDAC3 is a promising target in several diseases." (PMID 38140000, 2023). "Pharmacological inhibition of HDAC3 with RGFP966, a selective inhibitor of HDAC3, or genetic deletion of HDAC3, attenuated the renal fibrosis." (PMID 35559244, 2022). "By interacting with NCoR and NF-κB, HDAC3 triggered myofibroblast transdifferentiation and aggravated renal fibrosis." (PMID 34301918, 2021). "In mice with renal fibrosis induced by unilateral ureter obstruction, the expression levels of HDAC3 in the nucleus of renal tubular cells were significantly elevated in a TGF-β/Smad signaling-dependent manner." (PMID 34301918, 2021). "The renal fibrosis-induced HDAC3 upregulation was reversed by the selective inhibition of Smad3 phosphorylation." (PMID 34301918, 2021). "Given that hyperactive TGFβ often causes excessive macrophage phagocytic activities potentially leading to fibrotic evolution, the inhibition of the TGF-β-HDAC3/Smad-TIMAP pathway could represent a strategy to slow down the progression of renal fibrosis." (PMID 38474021, 2024). "Also, in a rat model of hyperuricemia-induced fibrosis, the depletion of HDAC3 via a genetic approach blunted renal fibrosis." (PMID 39050859, 2024). "HDAC3 aberration can inhibit Klotho transcription and promote renal fibrosis." (PMID 36263180, 2022). "Thus, although our data implicate HDAC11 in NF-κB–mediated inflammatory and fibrogenic responses, additional studies will be required to determine whether HDAC11 acts independently or in cooperation with HDAC3 to regulate NF-κB signaling during renal fibrosis." (PMID 41275091, 2025). "Therefore, inhibition of the TGF-β-HDAC3/Smad-TIMAP pathway may slow down the progression of TGF-β-mediated renal fibrosis." (PMID 36148005, 2022).
renal fibrosis (continued). "In mouse models of renal fibrosis induced by unilateral ureteral obstruction and aristolochic acid I, RASAL1 suppression coincided with a preferential increase in HDAC3." (PMID 41624795, 2026). "Fibroblast-specific Hdac3 knockout mice exhibited preserved RASAL1 expression, attenuated FMT, and reduced renal fibrosis compared to wild-type controls." (PMID 41624795, 2026). "HDAC3 also regulates macrophage function, promotes macrophage M2 polarization activation and leads to MMT, which is a marker of renal fibrosis." (PMID 37455912, 2023). "However, in the adenine CKD mouse model, the application of trichostatin A and the specific knockdown of HDAC3 facilitate PPARγ acetylation, leading to the upregulation of KLOTHO protein and the concurrent inhibition of renal fibrosis." (PMID 38929505, 2024). "Similarly, it has been reported that inhibition of HDAC3 and HDAC8 derepressed klotho expression during renal fibrosis." (PMID 38794880, 2024). "In addition, HDAC3 inhibited the expression of klotho by recruiting NCoR and NF-κB to form a complex that acts on the klotho promoter, thereby promoting the progression of renal fibrosis, developing a pro-fibrotic pathway initiated by TGF-β with HDAC3 as an intermediary." (PMID 36148005, 2022).
acute myeloid leukemia (15 papers, 2013 to 2025). Acute myeloid leukemia (AML) is a group of neoplasms arising from precursor cells committed to the myeloid cell-line differentiation. "In acute myeloid leukaemia, the up-regulation of HDAC3-AKT-P21-CDK2 signalling has been associated with poor survival." (PMID 38732271, 2024). "Selective inhibition of FLT3, HDAC3 or HDAC6 have been proved useful for the treatment of acute myeloid leukemias, but the benefits of combinations of HDAC3, HDAC6 and FLT3 inhibitors were rarely reported." (PMID 29262547, 2017). "Similarly, in acute myeloid leukemia, HDAC3 promoted chemotherapy resistance by deacetylating and activating AKT in response to genotoxic stress." (PMID 41326348, 2025). "Additionally, crotonoside has been reported to be capable of suppressing acute myeloid leukemia via inhibiting Fms-like tyrosine kinase 3 (Flt3) and HDAC3/6 pathways." (PMID 33182776, 2020). "For example, c-Myc could bind on miR-451 promoter region and suppress miR-451⊣YWTAZ/AKT axis via recruiting HDAC3 in acute myeloid leukemia." (PMID 31238581, 2019). "In acute myeloid leukemia (AML), oncogenic protein c-myc recruits HDAC3 to form a suppressive complex binding to the promoter of miR-451 gene, inhibiting the expression of this tumor suppressive microRNA." (PMID 35646715, 2022). "For instance, in acute myeloid leukemia (AML), the transcriptional complex NF-κB/Sp1 can interact with HDAC1 and HDAC3 to form the NF-κB/Sp1/HDAC complex on miR-29b enhancer, which resulted in the silencing of miR-29b." (PMID 24261995, 2013). "A non-epigenetic role of HDAC3 in acute myeloid leukemia (AML) responsible for resistance to anthracyclines and cytarabine has been reported." (PMID 39624079, 2024).